BRD4 (bromodomain containing 4)
Diseases named in the same sentence as BRD4 in open-access papers (continued):
Sharing a sentence is not in itself a finding about the gene and the disease.
cardiac hypertrophy (15 papers, 2019 to 2025). "Gaelle Auguste demonstrated that treatment with the BRD4 inhibitor JQ1 partially reverses the transcript levels of molecular markers of cardiac hypertrophy and cardiac dysfunction in LMNA-deficient cardiomyocytes." (PMID 39215370, 2024). "As a key potential therapeutic target, BRD4 has been implicated in many heart diseases, including pathological cardiac hypertrophy." (PMID 37528096, 2023). "High glucose induction to H9C2 cells (a cell line to study cardiac pathogenesis in vitro) causes cardiac hypertrophy and increases the expression of BRD4, which was further confirmed by the in vivo model of diabetic rats." (PMID 35401196, 2022). "This study aimed to investigate the mechanism underlying the effects of BRD4 on cardiac hypertrophy." (PMID 36247184, 2022). "Although inhibition of BRD4 suppresses cardiac hypertrophy and pathologic cardiac remodeling, cardiomyocyte-specific deletion of BRD4 in mice triggers progressive deterioration of cardiac contractile function and eventually lead to dilated cardiomyopathy." (PMID 40695797, 2025). "Another study revealed that during cardiac hypertrophy, ROS promoted BRD4 expression in mouse cardiomyocytes." (PMID 39215370, 2024). "Bromodomain-containing protein 4 (BRD4) plays a key role in cardiovascular diseases such as cardiac hypertrophy, infarction, and fibrosis as an epigenetic regulator." (PMID 37528096, 2023). "BRD4 is being increasingly acknowledged as a key epigenetic regulator during cardiac hypertrophy and fibrosis processes." (PMID 37528096, 2023). "Considering that Nox4, a gene downstream of BRD4, is a major resource for ROS in the heart and can promote cardiac hypertrophy mediated through the Nox4/ROS/ADAM17 pathway, the change in Nox4 protein and mRNA was analysed first." (PMID 37528096, 2023). "BRD4 is upregulated in cardiac hypertrophy and thus plays a crucial role in stress response during cardiac disease." (PMID 38089921, 2023). "In our study, BEL reduced both the mRNA and protein levels of BRD4 during ISO-induced cardiac hypertrophy." (PMID 37528096, 2023). "Our findings showed that BRD4 silencing has protective effects by inhibiting cardiac hypertrophy, oxidative stress, and inflammation in H9c2 cells induced by Ang II." (PMID 36247184, 2022). "BRD4 is one of the main culprits of cardiac injuries, including cardiac hypertrophy, infarction congestive heart failure, and vascular smooth muscles remodeling." (PMID 35401196, 2022). "This showed that BRD4 is an inducer of cardiac hypertrophy, which was supported by a recent report that Ang II-induced cardiomyocyte hypertrophy was attenuated by BRD4 decrease." (PMID 36247184, 2022). "BRD4 silencing by siRNA markedly suppressed cardiac hypertrophy, apoptosis, oxidative stress, and pro-inflammatory cytokine production." (PMID 36247184, 2022). "A high expression of BRD4 was found during cardiac hypertrophy induced by phenylephrine and high glucose (HG) and suppressed by JQ1, which is a specific BRD4 inhibitor." (PMID 36247184, 2022). "Among the four BET family members, BRD4 has been widely reported to be involved in regulation of cardiac hypertrophy." (PMID 35694272, 2022). "The cardioprotective effects of BRD4 silencing, including cardiac hypertrophy, oxidative stress, and inflammatory cytokine production, were all significantly attenuated by TLR4 overexpression." (PMID 36247184, 2022). "TLR4 overexpression attenuated cardioprotection against Ang II by BRD4 silencing, including cardiac hypertrophy, oxidative stress, and inflammatory cytokine production." (PMID 36247184, 2022). "Bromodomain-containing protein 4 (BRD4) is involved in various cellular processes, including cardiac hypertrophy." (PMID 36247184, 2022). "The promotive effect of BRD4 on cardiac hypertrophy was also observed in H9c2 cells incubated with high glucose." (PMID 36247184, 2022).
cardiac hypertrophy (continued). "The present study identified BRD2 as a novel regulator in cardiac hypertrophy, with a distinct mechanism from BRD4." (PMID 35694272, 2022). "Recently, acetylated histones together with BRD4 and their genomic distribution reveals their role in cardiac hypertrophy." (PMID 35958418, 2022). "Our results are in accordance with other reports that BRD4 expression is influenced by phenylephrine or high-glucose levels, which are two inducers of cardiac hypertrophy." (PMID 36247184, 2022). "BRD2 was remarkably elevated at the transcriptional level in parallel with BRD4, suggesting that BRD2 is probably associated with the pathological progression of cardiac hypertrophy." (PMID 35694272, 2022). "Hypertrophy induced stimulation significantly down-regulates miR-9, and BRD4 recruits the super enhancer gene region to initiate cardiac hypertrophy." (PMID 35958418, 2022). "In conclusion, Ang II increases the mRNA and protein expressions of BRD4 and promotes cardiac hypertrophy, oxidative stress, and inflammatory cytokine production." (PMID 36247184, 2022). "Meanwhile, BRD4 silencing protects against Ang II-induced cardiac hypertrophy via the upregulation of Nrf2-HO-1 and downregulation of TLR4-NF-κB signaling pathways." (PMID 36247184, 2022). "BRD4 has been shown to activate P-TEFb (positive transcription extension factor b) recruitment and transcriptional suspension release, promoting cardiac hypertrophy." (PMID 35958418, 2022). "BRD4 blockers reduce pathological cardiac hypertrophy by reducing ROS production and inhibiting fibrosis and inflammation." (PMID 34336890, 2021). "Previous studies indicated that BRD4 acted as a central co-activator of transactivation of pathological genes during cardiac hypertrophy." (PMID 32392533, 2020). "We first investigated whether BRD4-mediated Nox4 inhibition contributes to BEL efficacy in ISO-induced cardiac hypertrophy." (PMID 37528096, 2023). "Thus, BEL alleviated cardiac hypertrophy and cardiac dysfunction via the BRD4/Nox4/ROS axes during ISO-induced cardiac hypertrophy." (PMID 37528096, 2023). "BRD4 is an important gene transcription activator in cardiac hypertrophy and heart failure." (PMID 35401196, 2022). "As Ang II also simultaneously induced cardiac hypertrophy, this indicates that BRD4 might involve the process of cardiac hypertrophy." (PMID 36247184, 2022). "Notably, BRD2 shares close similarity in structure and physiological role with BRD4, which is well-accepted to be a nodal regulator of cardiac hypertrophy." (PMID 35694272, 2022). "BRD4, as a member of BETs, is generally considered to be increased in cardiac hypertrophy." (PMID 35958418, 2022). "Our results speculate that the BRD4/TLR4 axis might be a promising strategy for treating cardiovascular diseases with cardiac hypertrophy, including HF." (PMID 36247184, 2022). "As a BRD4 inhibitor, JQ1 is firstly discovered as an anti-tumor compounds, but growing evidences indicate that JQ1 becomes a recognized anti-inflammatory tool to study the functions of BRD4 particularly in inflammation-related diseases, such as cardiac hypertrophy and periodontitis." (PMID 33679744, 2021). "In addition, the results from an increasing number of studies has shown that Brd4 is involved in the development of pulmonary fibrosis, cardiac hypertrophy, osteoarthritis and intervertebral disk degeneration." (PMID 32982695, 2020). "Therefore, our results provide important insights into the molecular mechanisms underlying the cardioprotective effects of BRD4 silencing, which may help the development of novel therapeutic strategy for BRD4 inhibitor in the treatment of cardiac hypertrophy." (PMID 36247184, 2022). "Thus, the lack of long CTD in BRD2 might exclude the possibility that BRD2 regulates cardiac hypertrophy in a similar mechanism as BRD4." (PMID 35694272, 2022). "However, the roles of BET family members, except BRD4, remain unknown in pathological cardiac hypertrophy." (PMID 35694272, 2022).
cardiac hypertrophy (continued). "Therefore, the present findings that BRD2 regulates cardiac metabolism might elucidate a unique mechanism of BET family in the regulation of cardiac hypertrophy, in addition to that of BRD4 with the function of long CTD." (PMID 35694272, 2022). "Interestingly, Brd4 expression has been reported to be markedly increased in cardiomyocytes subjected to oxidative stress, indicating that oxidative stress induced by Brd4 is involved in cardiac hypertrophy." (PMID 32982695, 2020). "The results showed that BEL was not able to reduce ISO-induced ANP and BNP protein levels after the reversal of BRD4 protein, which illustrated that BEL ameliorated cardiac hypertrophy through its inhibitory function on BRD4." (PMID 37528096, 2023). "In this study, we explored the therapeutic effect of BEL on cardiac hypertrophy and elucidated the mechanism by which BEL confers myocardial protection through the BRD4/Nox4 pathway." (PMID 37528096, 2023). "Our study showed that the mRNA and protein of TLR4 were reduced by BRD4 silencing in H9c2 cells with Ang II, and TLR4 overexpression could attenuate cardiac hypertrophy change, oxidative stress, and inflammatory cytokine production." (PMID 36247184, 2022). "One explanation for this apparent contradiction is that BRD4 protein expression is increased during the TAC-induced cardiac hypertrophy even though it is not consistently reported." (PMID 30934680, 2019). "However, the present data did not allow to speculate whether the regulatory mechanism of BRD2 and BRD4 in cardiac hypertrophy are connected or not." (PMID 35694272, 2022). "However, BRD4 possesses a longer CTD with a unique function that could facilitate the recruitment of P-TEFb complex to promote transcriptional elongation of hypertrophic genes, finally contributing to cardiac hypertrophy." (PMID 35694272, 2022). "The present results that BRD2 exerted pro-hypertrophic effects in cardiomyocytes, apart from the previously reported BRD4, might help to explain the promising effect of pan-BETi in treatment of pathological cardiac hypertrophy, rather than specific inhibitor of a single BET member." (PMID 35694272, 2022). "These experiments illustrated that BRD4 acted upstream of Nox4 and that Nox4 did not affect BRD4 protein levels, although both molecules were regulated by BEL, inhibiting genes related to cardiac hypertrophy individually." (PMID 37528096, 2023).
pulmonary fibrosis (15 papers, 2016 to 2025). Chronic progressive interstitial lung disorder characterized by the replacement of the lung tissue by connective tissue, leading to progressive dyspnea, respiratory failure, or right heart failure. "Previous studies have implicated BRD4 as a key target in fibrotic gene networks, including those involved in lung fibrosis." (PMID 40809038, 2025). "Furthermore, in addition to its significant involvement in inflammation, oxidative stress, and fibrosis in pulmonary fibrosis, BRD4 has also been associated with various other lung-related diseases." (PMID 39215370, 2024). "To explore potential therapeutic interventions, we evaluated CPI-0610, a BET inhibitor targeting BRD4, as a novel treatment strategy for arsenical-induced pulmonary fibrosis (PF)." (PMID 40809038, 2025). "Our study provides the first experimental evidence that BRD4 inhibition via CPI-0610 attenuates the development of pulmonary fibrosis following cutaneous lewisite exposure in mice." (PMID 40809038, 2025). "Taken together, BRD4 contributes to pulmonary fibrosis disease progression by participating in multiple signaling pathways involved in TGF-β/Smad signaling." (PMID 39215370, 2024). "BRD4 inhibition effectively mitigates the progression of pulmonary fibrosis and COPD while also ameliorating PAH and acute lung injury." (PMID 39215370, 2024). "In summary, we concluded that BRD4 can serve as a target in pulmonary fibrosis and has the potential to serve as a therapeutic target in lung diseases such as airway remodeling, interstitial lung disease, PAH and COPD." (PMID 39215370, 2024). "Altogether, these data indicate that inhibition of BRD4 activity by ZL0591 diminishes bleomycin-induced pulmonary fibrosis, possibly due to inhibition of myofibroblast transdifferentiation." (PMID 35782526, 2022). "Here, we explore the role of the BRD4 BD1 in myofibroblast transdifferentiation in a mouse model of interstitial pulmonary fibrosis." (PMID 35782526, 2022). "It has been shown that NADPH oxidase 4 (Nox4) is downregulated in idiopathic pulmonary fibrosis myofibroblasts by Brd4 inhibition." (PMID 34149421, 2021). "Among the eight m6A-SARS-CoV-2 related genes in BAL cells, BRD4 appears to be the most promising drug target for pulmonary fibrosis." (PMID 33647885, 2021). "However, the exact mechanisms by which BRD4 inhibition ameliorates pulmonary fibrosis by suppressing inflammation remain to be further explored." (PMID 39215370, 2024). "What are the specific pathways by which BRD4 participates in the process of pulmonary fibrosis?" (PMID 39215370, 2024). "Previous research has shown that in the context of pulmonary fibrosis, BRD4 regulates the expression of NF-κB dependent EMT genes, suggesting that a similar mechanism could be at play in tumors as well." (PMID 37461511, 2023). "BRD4 regulates expression of Nox4, an enzyme required for TGFβ-induced production of reactive oxygen species and fibroblast to myofibroblast transition in pulmonary fibrosis." (PMID 35782526, 2022). "In this study, we applied this selective inhibitor to test whether BRD4 BD1 mediated pulmonary fibrosis in the bleomycin mouse model of the disease." (PMID 35782526, 2022). "This work reveals that BRD4 BD1 plays a critical role in the progression of bleomycin-induced pulmonary fibrosis in mice and that targeting this epigenetic regulator may be a useful strategy for anti-fibrotic therapies in the human disease." (PMID 35782526, 2022). "It was found that BRD4 was involved in pulmonary fibrosis by downregulating signals after growth factor stimulation, driving TGF-β-induced NOX4 expression in human lung fibroblasts, and mediating NF-kappaB-dependent epithelial-mesenchymal transition of airway epithelium." (PMID 33647885, 2021). "Brd4 has been reported to moderate TGF-β 1-mediated α-SMA induction in lung fibrosis." (PMID 27732564, 2016).
pulmonary fibrosis (continued). "Similarly, pharmacologic inhibition of BRD4 with JQ1 reverses bleomycin-induced lung fibrosis in mice, including reduced tissue hydroxyproline and Collagen I staining, indicating that BRD4 inhibition can reduce tissue stiffness-associated profibrotic signaling." (PMID 27990121, 2016). "Collectively, this evidence suggests that BRD4 is involved in promoting NOX4 expression and mediating oxidative stress-induced pulmonary fibrosis." (PMID 39215370, 2024). "In organ fibrosis, OTX015 was able to inhibit the binding of BRD4 and NOX4 promoters, reducing ROS levels in fibroblasts and attenuating pulmonary fibrosis in mice." (PMID 39215370, 2024). "Recently, Bernau and colleagues further showed the efficacy of selective inhibition of the BRD4 BD1 domain in reducing myofibroblast differentiation and reversing established pulmonary fibrosis in mice using the BRD4 BD1-selective inhibitor ZL0591." (PMID 37686037, 2023). "Two papers from the same research group emerged a few years later that investigated the role of BET proteins in pulmonary fibrosis, which represent a milestone for targeting BET/BRD4 in this context." (PMID 37686037, 2023). "We conclude that BRD4 BD1 interactions are critical for myofibroblast transdifferentiation and fibrotic progression in a mouse model of pulmonary fibrosis." (PMID 35782526, 2022). "Moreover, the dual advantage of using SF2523 is that since BRD2/BRD4 induces pro‐fibrotic genes and promotes lung tissue fibrosis, which is majorly seen in COVID‐19 patients; therefore, inhibition of BRD2/BRD4 may prevent lung fibrosis and promote fast recovery as well." (PMID 35942238, 2022). "Studies have shown that BRD4 is involved in EMT and airway remodeling in asthma, airway inflammation, and pulmonary fibrosis." (PMID 32923445, 2020). "Studies have shown that BRD4 participates in tissue remodeling or EMT in carcinoma, asthma, and pulmonary fibrosis." (PMID 32923445, 2020). "In addition, the administration of CG223, a quinolone BRD4 inhibitor designed and synthesized by Shunya Kaneshita, significantly attenuated BLM-induced pulmonary fibrosis." (PMID 39215370, 2024). "Therefore, BRD4 inhibition could block the TGF-β1 signaling pathway to a certain extent, thus exerting an anti-pulmonary fibrosis effect." (PMID 39215370, 2024). "Importantly, our finding that Brd3 and Brd4, but not Brd2, are involved in NOX4 regulation by TGF-β suggests that a degree of selectivity may be possible when considering BET inhibitors as possible therapeutic agents in pulmonary fibrosis." (PMID 31119153, 2019).
lung adenocarcinoma (14 papers, 2014 to 2026). A carcinoma that arises from the lung and is characterized by the presence of malignant glandular epithelial cells. "CK2-mediated BRD4 phosphorylation promotes resistance to BET inhibitors in lung adenocarcinoma, while CK2 inhibitors reduce resistance." (PMID 38381246, 2024). "We consistently found that a high expression level of BRD4 was observed in lung adenocarcinoma, which predicted a poor prognosis in the Kaplan–Meier Plotter database." (PMID 35988145, 2022). "This suggests that CK2 phosphorylation of BRD4 may be related to the JQ1-resistant lung adenocarcinoma (LAC) cell line." (PMID 35402244, 2022). "Moreover, immunofluorescence of ERRα and BRD4 in tissue sections of 3 patients with lung adenocarcinoma also showed that they were widely co-localized in tumor tissues, but isolated from each other in adjacent tissues." (PMID 36216804, 2022). "Additionally, results from the drug-resistant cells suggest that CDK9 inhibitors, alone or in combination with sublethal doses of BRD4 inhibitor, would be efficacious for patients who are burdened with K-Ras or EGFR mutated lung adenocarcinomas and those who have developed therapy resistance." (PMID 34359807, 2021). "In the JQ1-resistant lung adenocarcinoma (LAC) cell line, the phosphorylation of BRD4 was increased, and CK2 was identified as its kinase." (PMID 35402244, 2022). "The relative amplification of the genes varied substantially across the cancer types, with SETDB1 amplified in 20% of lung adenocarcinomas, NSD3 amplified in 21% of lung squamous cancers, and BRD4 amplified in 17% of ovarian serious adenocarcinomas." (PMID 24874471, 2014). "Further studies showed that JQ1 combined with CK2 inhibitor (CX-4945) could effectively induce the death of lung adenocarcinoma cells and determined the CK2 phosphorylation of BRD4 as a potential target to overcome this cancer resistance." (PMID 35402244, 2022). "BRD4 and FAK exhibit an upregulation in 34% (21 out of 61) lung adenocarcinomas." (PMID 32793596, 2020).